MKNK2 (MAPK interacting serine/threonine kinase 2)
Description:
Serine/threonine-protein kinase that phosphorylates SFPQ/PSF, HNRNPA1 and EIF4E. May play a role in the response to environmental stress and cytokines. Appears to regulate translation by phosphorylating EIF4E, thus increasing the affinity of this protein for the 7-methylguanosine-containing mRNA cap. Required for mediating PP2A-inhibition-induced EIF4E phosphorylation. Triggers EIF4E shuttling from cytoplasm to nucleus. Isoform 1 displays a high basal kinase activity, but isoform 2 exhibits a very low kinase activity. Acts as a mediator of the suppressive effects of IFNgamma on hematopoiesis. Negative regulator for signals that control generation of arsenic trioxide As(2)O(3)-dependent apoptosis and anti-leukemic responses. Involved in anti-apoptotic signaling in response to serum withdrawal.
Synonyms: Mnk2; GPRK7
Tractability: Small molecule: a drug acting on it is in phase 2 or 3 trials; a structure with a bound ligand is known; a high-quality ligand is known; it has a high-quality binding pocket; it belongs to a druggable protein family. PROTAC: it is named in the literature on targeted protein degradation; ubiquitination databases record sites on it; a small molecule that binds it is known.
Target class: Protein Kinase; CAMK protein kinase group; CAMK protein kinase MNK subfamily; Enzyme; Kinase; CAMK protein kinase MAPKAPK family
Chemical probes: PD081456, PD081605, PD082875, tomivosertib (high quality)
Gene: Protein-coding gene on chromosome 19 (2,037,465 to 2,061,220, reverse strand). Ensembl gene ENSG00000099875.
Subcellular location: Nucleus, PML body (Isoform 2); Cytoplasm (Isoform 1)
Subcellular location (Human Protein Atlas): Nuclear bodies; Cytosol; Nucleoplasm
Gene Ontology:
Molecular function: ATP binding; protein binding; protein serine kinase activity; protein serine/threonine kinase activity; protein kinase activity
Biological process: cellular response to arsenic-containing substance; hemopoiesis; intracellular signal transduction; protein phosphorylation; cell surface receptor signaling pathway
Cellular component: cytosol; nuclear body; cytoplasm; PML body
Genetic constraint (gnomAD): Loss-of-function variants: 60 observed, 50.84 expected, observed/expected ratio (o/e) 1.18, 90% interval 0.96 to 1.46. The synonymous counts are far from expectation, so gnomAD's model fits this gene poorly and the ratio says little. Missense variants: 683 observed, 560.58 expected, observed/expected ratio (o/e) 1.22, 90% interval 1.14 to 1.3. Synonymous variants: 323 observed, 228.12 expected, observed/expected ratio (o/e) 1.42, 90% interval 1.29 to 1.55.
Homologues: Orthologues: chimpanzee MKNK2 (99% identical), macaque MKNK2 (99% identical), guinea pig MKNK2 (95% identical), pig MKNK2 (94% identical), dog MKNK2 (94% identical), mouse Mknk2 (93% identical), rat Mknk2 (85% identical), tropical clawed frog mknk2 (78% identical), zebrafish mknk2b (77% identical), zebrafish mknk2a (75% identical), Drosophila melanogaster Lk6 (51% identical), Caenorhabditis elegans mnk-1 (43% identical). Paralogues in human: MKNK1 (63% identical), CAMK4 (27% identical), MAPKAPK5 (25% identical), MAPKAPK3 (25% identical), MAPKAPK2 (24% identical), DCX (13% identical).
Diseases named in the same sentence as MKNK2 in open-access papers:
MKNK2 is named in the same sentence as 49 diseases in open-access papers, as found by Europe PMC text mining. Sharing a sentence is not in itself a finding about the gene and the disease. The quoted sentences say what the papers report.
gastric cancer (4 papers, 2021 to 2025). A primary or metastatic malignant neoplasm involving the stomach. "The present study also found a positive correlation of MKNK2 with memory B cells, regulatory T cells (Tregs), and CD8 T cells in gastric cancer, all of which are reported to be strongly associated with tumors." (PMID 34222004, 2021). "According to another study, regulating the alternative splicing of MKNK2 by binding to MNK2 pre‐mRNA at e14a induces down expression of MNK2a splicing and regulates the p38 MAPK/PPARα signaling pathway to promote gastric cancer peritoneal metastasis." (PMID 40052233, 2025). "In contrast, the expression of MKNK2 and PAPPA2 was significantly higher in paraneoplastic tissues than in gastric cancer tissues (Figures 15C1–F2)." (PMID 34222004, 2021). "The CGB5, MKNK2, and PAPPA2 genes may serve as important biomarkers for predicting the prognosis of gastric cancer." (PMID 34222004, 2021). "CGB5, MKNK2, and PAPPA2 may be used as novel prognostic biomarkers for gastric cancer." (PMID 34222004, 2021).
ovarian carcinoma (4 papers, 2014 to 2024). A malignant neoplasm originating from the surface ovarian epithelium. "It has been described that miR-125b could induce autophagy through its interaction with Foxp3 in thyroid cancer cells and modulate autophagy in drug-resistant ovarian cancer cells using directly targeted MAP kinase interacting serine/threonine kinase 2 (MKNK2)." (PMID 37834215, 2023). "A recent study found a negative correlation between miR125b and MKNK2 in ovarian cancer tissue and further showed that miR-125 targeting of MKNK2 was promoting autophagy in chemo-resistant cancer cells." (PMID 35840794, 2022). "Our findings indicated that MAP kinase interacting serine/threonine kinase 2 (MKNK2) and laminin beta 2 (LAMB2) gene expression levels were downregulated in response to HE4 interference in ovarian cancer cells, whereas exogenous HE4 protein supplementation reversed this effect." (PMID 25362534, 2014).
prostate carcinoma (4 papers, 2014 to 2022). A carcinoma that arises from epithelial cells of the prostate gland. "Elevated expression of MKNK2 has been identified in multiple types of tumors, including melanoma, prostate cancer, and soft tissue sarcoma." (PMID 36209049, 2022).
glioblastoma (3 papers, 2018 to 2022). The most malignant astrocytic tumor (WHO grade IV). "For instance, manipulating AS of the mRNA for the kinase Mnk2 (MKNK2) with splice-switching oligonucleotides (SSOs) was reported as a novel approach to inhibit glioblastoma tumorigenesis." (PMID 32793502, 2020). "Taking into account its enhanced activity with chemotherapeutic drugs, MKNK2 splicing modulation can be examined as a single or combined therapy for glioblastoma." (PMID 30329087, 2018). "Although the present setting of the experiment is not a model for treatment in vivo, these results suggest that intracranially injected SSOs designed to modulate MKNK2 alternative splicing can reduce glioblastoma tumor burden in mice." (PMID 30329087, 2018). "Here, we present the development of an SSO to modulate the splicing of MKNK2 with potential to treat glioblastomas." (PMID 30329087, 2018). "Thus, we examined if MKNK2 splicing modulation by the 2b-block SSO can sensitize glioblastoma cell lines to chemotherapeutic agents such as, CDDP, doxorubicin and TMZ." (PMID 30329087, 2018). "Due to the unknown role of MKNK2 alternative splicing in glioblastoma development and progression, we sought to examine the ratio of MKNK2 splice isoforms in glioblastoma patient-derived samples." (PMID 30329087, 2018). "Thus, our results suggest that MKNK2 splicing modulation by SSOs can be developed as a novel therapy for glioblastoma." (PMID 30329087, 2018). "In this study we show that manipulation of MKNK2 alternative splicing, elevating Mnk2a levels, inhibited survival and anchorage-independent growth of several cancer cell lines, sensitized glioblastoma cells to chemotherapy and inhibited glioblastoma tumor growth in vivo." (PMID 30329087, 2018). "In light of the fact that Mnk2a acts as a tumor suppressor and is downregulated in several cancers, including glioblastoma, we hypothesized that manipulating MKNK2 splicing to elevate Mnk2a and reduce Mnk2b will inhibit glioblastoma development and progression." (PMID 30329087, 2018). "The alternative splicing of the murine Mknk2 mRNA does not occur in a mode similar to the human MKNK2, so the 2b-block SSO cannot be tested directly on mouse glioblastomas." (PMID 30329087, 2018).
glioma (3 papers, 2020 to 2022). A benign or malignant brain and spinal cord tumor that arises from glial cells (astrocytes, oligodendrocytes, ependymal cells). "Their study provides evidence on the therapeutic potential of manipulating MKNK2 alternative splicing as a novel approach to treat glioma." (PMID 33602301, 2021). "Across GBM subtypes, both MKNK1 and MKNK2 genes are highly expressed in mesenchymal subtype GBM, while only the MKNK1 expression correlates with the mesenchymal glioma stem cells marker CD44 and predicts poor survival in GBM when both genes are upregulated." (PMID 32340135, 2020).
Insulin resistance (3 papers, 2016 to 2023). Increased resistance towards insulin, that is, diminished effectiveness of insulin in reducing blood glucose levels. "Moreover, MKNK2-deficient male mice exhibit protection against HFD-induced obesity and insulin resistance." (PMID 36209049, 2022).
lung carcinoma (3 papers, 2019 to 2023). "It has been reported that SRSF1 was able to regulate EMT through disrupting the alternative splicing of key tumor associated genes, including Ron proto-oncogene, PRRC2C, and MKNK2, to modulate lung cancer progression." (PMID 31832019, 2019).
colon adenocarcinoma (2 papers, 2021 to 2022).
Obesity (2 papers, 2020 to 2022). Accumulation of substantial excess body fat. "Recent studies have found that disabling MKNK2 could protect against diet-induced obesity, which might result from greater ATP consumption, mitochondrial oxidative metabolism, and other energy utilization processes." (PMID 36209049, 2022). "We also show that mitogen-activated protein kinase (MAPK)-interacting kinase 2 (MNK2; Mknk2), which plays a distinct role in diet-induced obesity, is induced during early adipogenesis and identify the functional DNA response elements responsible for regulating its expression." (PMID 32787498, 2020).
brain injury (1 paper, 2025). Acute and chronic (see also brain INJURIES, CHRONIC) injuries to the brain, including the cerebral hemispheres, CEREBELLUM, and brain STEM. "Our findings reveal an important role of the KLF7/MKNK2/HIF‐1 axis in IS, and targeting this axis may be a promising strategy to alleviate IS‐induced brain injury." (PMID 40923147, 2025).
cerebral infarction (1 paper, 2025). An ischemic condition of the brain, producing a persistent focal neurological deficit in the area of distribution of the cerebral arteries. "In contrast, reactivation of MKNK2 not only offset the alleviation of the cerebral infarction by KLF7 overexpression but also exacerbated this pathology." (PMID 40923147, 2025).
MELAS (1 paper, 2017). "Apart from many targets including PINK1, FOXO1, PPARγ and Apaf-1 investigated before, MKNK2, GREM1 and EEF1A1 that might be potential targets of miR-27b-3p were revealed in the regulatory network of MELAS pathogenesis." (PMID 28139706, 2017).
Stroke (1 paper, 2020). Sudden impairment of blood flow to a part of the brain due to occlusion or rupture of an artery to the brain. "Furthermore, stroke induced the upregulation of genes involved in PI3K-Akt suppression, such as eIF4EBP1 and Mknk2." (PMID 32629989, 2020).
tumor (29 papers, 2012 to 2026). "The gene encoding kinase Mnk2 (MKNK2) can be spliced to generate either a pro-oncogenic isoform Mnk2b or a tumor-suppressive isoform Mnk2a." (PMID 39885614, 2025). "Overexpression of SRPK1/2 in colon adenocarcinoma (CAC) enhances SRSF1 phosphorylation, which subsequently leads to MKNK2 AS into MKNK2b, ultimately promoting tumor growth." (PMID 39885614, 2025). "Compared with several other tumor types, we found an inverse relationship between MKNK2 and the M2 markers CD163 and MRC1 (CD206) in human PDAC tumors." (PMID 35380995, 2022). "High nucleus SRSF1 promoted MKNK2 splicing into MKNK2b instead of MNK2a, consequently enhanced tumor proliferation." (PMID 33602301, 2021). "We previously found that MKNK2 alternative splicing can generate a tumor suppressive isoform (Mnk2a) and an oncogenic isoform (Mnk2b)." (PMID 30329087, 2018). "We found that the 2′-OMe phosphorothioated backbone 2b-block SSO both induced a shift in MKNK2 splicing in vivo and inhibited tumor growth." (PMID 30329087, 2018). "Furthermore, two events overexpressed in the tumor tissues on the MKNK2 and FGFR1OP genes displayed very strong affinity for MHC-I and a corresponding WT event without MHC-I binding affinity." (PMID 39796063, 2024). "In contrast, we didn’t identify any significant correlation between MKNK2 mRNA levels with lymph node (LN) metastasis, indicating MKNK2 may have little effect on modulating tumor invasion." (PMID 33602301, 2021). "Merestinib is a potent inhibitor of NTRK, it also targets additional kinases such as the TAM receptors (AXL, MERTK, and TYRO3), and MKNK1 and MKNK2, which may also contribute to anti-tumor growth." (PMID 30885237, 2019). "Based on the findings that Mnk2a acts as a tumor suppressor and its production competes with the production of the oncogenic Mnk2b isoform, we focused our efforts on the manipulation of MKNK2 alternative splicing to induce Mnk2a formation, in order to inhibit cancer cell growth and survival." (PMID 30329087, 2018). "It is important to point out that while merestinib is a potent inhibitor of NTRK, it also targets additional kinases such as the TAM receptors (AXL, MERTK, and TYRO3), and MKNK1 and MKNK2, which may also contribute to anti-tumor growth." (PMID 29568395, 2018). "Furthermore, 2′-O-methylated SSO, targeting the 3′-splice site in exon 14b of MKNK2 mRNA, enhances the tumor-suppressor Mnkn2a isoform levels, leading to increased phosphorylation and activation of p38α–MAPK and overexpression of cFOS, COX2 and IL-6 target genes." (PMID 32596243, 2020). "By analyzing the mRNAs level of MKNK2 isoforms in 32 paired tissues, we found that MKNK2a was downregulated in CAC tumor tissues while MKNK2b was upregulated." (PMID 33602301, 2021). "SRSF6 can regulate the alternative splicing of tumor-related genes, such as the insulin receptor INSR, the kinase Mnk2 (MKNK2) and the tumor suppressor gene DLG-1, thereby mediating tumorigenesis 70-72." (PMID 32760211, 2020). "In nontumorous cell, MKNK2 pre-mRNA is predominantly spliced into MKNK2a and translated to Mnk2a protein, which exerts anti-tumor effects." (PMID 33602301, 2021).
cancer (24 papers, 2014 to 2025). A tumor composed of atypical neoplastic, often pleomorphic cells that invade other tissues. "On another note, the finding that Mknk2 is regulated by cAMP and glucocorticoids may provide a useful insight into certain types of cancers in which MNK2 is highly expressed and associated with poor prognosis." (PMID 32787498, 2020). "Some selective inhibitors of MKNK2 have entered clinical trials, and display significant activity against several cancers." (PMID 36209049, 2022). "Recently, efforts are focused on the manipulation of MKNK2 (MAPK Interacting Serine/Threonine Kinase 2 gene) AS with the aim to inhibit cancer cell growth and survival." (PMID 34356101, 2021). "In accordance, the modulation of MKNK2 AS by a set of Splice–Switching antisense oligonucleotides (SSOs), increased Mnk2a levels which led to inhibition of cancer cell lines growth." (PMID 34356101, 2021). "The KIRP N-model includes an isoform in the MAP kinase MKNK1, suggesting a similar involvement in cancer as MKNK2." (PMID 27535130, 2016). "For example, alternative splices MKNK2-b and PKM2 promote gemcitabine resistance, while the p61BRAF (V600E) splice isoform reduces cancer cell sensitivity to vemurafenib." (PMID 39404386, 2024). "As an important serine/threonine kinase, MKNK2 has been identified to phosphorylate and activate the p38-MAPK pathway, thereby increasing cancer cell death." (PMID 36209049, 2022). "In addition, we establish the feedback activation of translation of key cancer growth-promoting proteins such as p90-RSK1 and MKNK2 that signals to eIF4E-eIF4A dependent translation following mTOR inhibition." (PMID 36900235, 2023). "Given that we tested multiple SSOs that did not affect MKNK2 splicing and did not inhibit the growth/survival of cancer cells, we are confident that this effect is specific." (PMID 30329087, 2018).
infection (2 papers, 2021 to 2022). The state of being infected such as from the introduction of a foreign agent such as serum, vaccine, antigenic substance or organism. "The western blot assay confirmed that protein expression of MKNK2 was significantly increased in cardiomyocytes after Ad-MKNK2 infection." (PMID 36209049, 2022).
neurodevelopmental disorder (1 paper, 2025). A behavioral and cognitive disorder with onset during the developmental period that involves impaired or aberrant development of intellectual, motor, or social functions. "Downregulation of Mknk2 can impair eIF4E phosphorylation, leading to translational repression and disrupted protein synthesis, a mechanism increasingly implicated in neurodevelopmental disorders such as RTT." (PMID 41009596, 2025).
MKNK2 also shares sentences with these, for which no sentence is quoted: breast carcinoma (4 papers); acute myeloid leukemia (3); Anxiety (2); colorectal cancer (2); depression (2); diabetes (2); Glucose intolerance (2); medulloblastoma (2); melanoma (2); non-small cell lung carcinoma (2); soft tissue sarcoma (2); adenocarcinoma (1); bladder cancer (1); bladder tumors (1); brain tumor (1); breast tumors (1); colon cancer (1); diffuse large B-cell lymphoma (1); Fever (1); HCMV infection (1); hepatocellular carcinoma (1); lung adenocarcinoma (1); lung injury (1); lymph node metastasis (1); lymphoma (1); metabolic disease (1); metabolic syndrome (1); myasthenia gravis (1); pancreatic ductal adenocarcinoma (1); pancreatic tumors (1).
A further 2 diseases each share a sentence with MKNK2 in 1 paper.